MMP2 (matrix metallopeptidase 2)
Diseases named in the same sentence as MMP2 in open-access papers (continued):
Sharing a sentence is not in itself a finding about the gene and the disease.
cancer (continued). "For example, gelatinases MMP-2 and MMP-9 are highly expressed in human cancer cells, and E-cadherin is mainly expressed in epithelial tissues and has a low expression level in cancer cells." (PMID 36812247, 2023). "The activation of MAPKs and NF-κB could upregulate the levels of MMP-2 and MMP-9 in cancer cells and other pathological conditions." (PMID 38069361, 2023). "Because cancer stem cells and matrix metalloproteinases play a key role in carcinogenesis, CD44, MMP-2, and MMP-9 may be the potential prognosticators for RCC." (PMID 36831550, 2023). "Moreover, cryptolepine downregulated WNT3a-induced expression of MMP2 and MMP9 genes, which are involved in cancer cell invasion." (PMID 37513937, 2023). "Additionally, we measured the expression of MMP2 and MMP9, which are indicators of cancer metastasis." (PMID 37744277, 2023). "Similar types of MMPs are increased in both cancers, namely, MMP-1, MMP-2, MMP-9, and MMP-11." (PMID 36982551, 2023). "Importantly, high levels of serum MMPs are also reliable biomarkers indicative of metastatic progression and are associated with poor survival in gastric (MMP-14) and breast (MMP-2 and MMP-9) cancer patients." (PMID 37350937, 2023). "Therefore, control of the levels and actions of MMPs, especially MMP-2 and MMP-9, is necessary to care for and/or cure cancer and AD." (PMID 36674771, 2023). "Moreover, EP1 seems to mediate enhanced matrix metalloproteinase-2 (MMP-2) expression by cAMP independent CREB phosphorylation, illustrating its importance in cancer invasion (Sun et." (PMID 36436093, 2023). "Follow-up pharmacodynamic experiments demonstrated that EJ significantly inhibited metastasis of cancer cells both in vitro and in vivo, and that the protein levels of STAT3, MMP-2, and MMP-9 could be dose-dependently reduced by EJ." (PMID 37049904, 2023). "E-cadherin expression was lower, whereas MMP2 expression was higher in the cancer tissues than in the normal tissues." (PMID 37225681, 2023). "In addition, KT suppressed the expression of HIF1α, MMP-2, and MMP-9, which also play a significant role in bone metabolism and metastasis of cancer." (PMID 36674719, 2023). "An increase in IL-8 associated with BRAF mutation has been demonstrated to be essential for the induction of MMP-2 and MMP-9 that contribute to cell migration and to angiogenesis enhancing cancer vascularization to support the oxygen retrieval and nutrient supply to cancer cells." (PMID 37627054, 2023). "In multiple cancer cells, researchers have identified thousands of OCT3/4 target genes involved in critical tumorigenesis pathway, such as PTEN signaling, TNC (metastasis) and MMP2(invasiveness)." (PMID 37476834, 2023). "Several studies have also shown that MMP-2 and MMP-9 play a key role in the invasion of cancer cells, and their increased expression is directly related to the malignancy and aggressiveness of cancer cells." (PMID 37700002, 2023). "Among MMPs, MMP-2 and MMP-9 have been reported to be involved in cancer progression and metastasis." (PMID 36674771, 2023). "In addition, S100A4 knockdown decreased the expression of MMP2, a promoter and mediator of EMT in cancer." (PMID 37033662, 2023). "Moreover, PTEN has been reported to inhibit cell invasion and migration by downregulation of the expression and enzymatic activity of MMP2 and MMP9 in multiple human cancers, including GC 27-30." (PMID 36778127, 2023). "Moreover, the observation connected with the results of all measurements performed for MMP-2 and MMP-9 in the tissues shows that MMP-9 is more involved in the growing and spreading of cancer cells in the bladder than MMP-2." (PMID 36979935, 2023). "Thus, matrix-degrading proteases, such as MMP-2, MMP-9, MMP-14 (MT1-MMP), and MMP-16 (MT3-MMP), were reported to be required for EMT progression of different cancer types." (PMID 36766694, 2023). "Activation of STAT3 could significantly increase the expression of the metastasis-related proteins MMP-2 and MMP-9 in cancer cells." (PMID 37049904, 2023).
cancer (continued). "The results reveal that the combination was most effective in decreasing cellular oxidants and increasing glutathione levels, while there was a significant decrease in cancer cell migration and invasion involved in the suppression of iNOS, ICAM-1, and MMP-2 proteins." (PMID 37575276, 2023). "The top 20 up‐ and down‐regulated genes between malignant and mesothelial populations showed expected markers, such as PVRL4 or COL5A2, as well as genes that suggested a metabolically active cancer cell phenotype (WNT7B) and reactive mesothelial cells (MMP2 and LRP1) (upper heatmap)." (PMID 37691350, 2023). "Although the actual inhibitory effect of these quinoline derivatives on cancer cell invasion or metastasis is not validated, at least they impair the proteolytic activity of MMP-2 mediated by MT1-MMP." (PMID 37681919, 2023). "The upregulation of MMPs (MMP2, MMP9, and MMP13) was also reported in cancers overexpressing IL-32 along with other EMT markers including vimentin, Slug, Snail, and ZEB1, as well as they are well known for their contribution to cancer metastatic." (PMID 35281008, 2022). "We also examined the expression of MMP-2 (Gelatinase A, or 72kDa Type IV Collagenase), another collagenase that is usually elevated together with MMP-9 in pathological conditions, including cardiac remodeling and cancer metastasis." (PMID 36432152, 2022). "CHE was found to downregulate the expressions of MMP-2 and MMP-9 through the PI3K/Akt/mTOR signaling pathway and change the cytoskeleton structure by reducing p-FAK, which inhibited the metastasis and invasion of cancer in a dose-dependent manner." (PMID 35721116, 2022). "Consequently, regulation of MMP-2 and MMP-9 are crucial for preventing cancer invasion and metastasis." (PMID 35458783, 2022). "Our team discovered that cancer-originated DNA can promote the stimulation of ERK1/2 and MMP2/9 in HCC cells, while cotreatment with sinobine hydrochloride reduces the expression of ERK1/2 and MMP2/9." (PMID 35860597, 2022). "MMP-2 is an anti-cancer drug target in several aggressive tumors, whereas MMP-9 inhibitors may prove useful in treating cancer in its early stages as well as multiple autoimmune diseases." (PMID 35955688, 2022). "The increase of several MMPs' expression and enzymatic activity, such as MMP-1, MMP-2, MMP-3, MMP-7, MMP-9, MMP-10, and MMP-14, correlates with the aggressiveness of different types of cancer, which leads to consider them as prognostic markers and targets of new therapeutic strategies." (PMID 36213817, 2022). "Furthermore, deflamin resulted not only in a significant reduction in MMP-2 and MMP-9 activity but also in impaired cancer cell migration and invasion in vitro." (PMID 36551666, 2022). "Moreover, NGAL forms complexes with both MMP-2 and MMP-9 in cancer cells, which are thought to be involved in regulating cell differentiation." (PMID 36293148, 2022). "The recruitment and activation of proteases such as MMP2 and MMP9 at invadopodia sites could promote the degradation of ECM so as to provide traction for cancer invasion and metastasis." (PMID 35957827, 2022). "What’s more, MMP2 and MMP9 had been reported closed related to migration and invasion of cancers." (PMID 36353142, 2022). "In addition, members of CAPN family have been reported to facilitate the invasion of THCA by inducing MMP2 and MMP9 secretion, which can contribute to extracellular matrix degradation during cancer cell migration." (PMID 36389799, 2022). "Notably, it has been revealed that SIRT1 deacetylates and upregulates the expression of matrix metalloproteinase-2 (MMP2), a zinc-dependent endopeptidase that degrades the extracellular matrix to promote the invasion of cancer cells." (PMID 36291902, 2022). "Finally, by considering the genes recapitulating IL-3 biological functions, we proposed a model, including IL-3Rα, SNAI1, ZEB1, VIM, CTNNB1, MMP2, SPRY2, and CD274, that remarkably discriminates cancer aggressiveness (AUC = 0.86 95% CI = 0.82–0.89)." (PMID 36010912, 2022).
cancer (continued). "Besides, EMT is closely related to over-expression of MMP2 and MMP9 that are also correlated with cancer cell invasion and metastasis." (PMID 36338704, 2022). "Additionally, EGCG can inhibit matrix metalloproteinases such as MMP-2 and MMP-9, which are usually elevated in cancer and considered as instruments for degrading the basement membrane and facilitating cell invasion." (PMID 35956766, 2022). "Furthermore, MMP-2 and MMP-9 can remarkably affect angiogenesis in malignant tumors by activating VEGF." (PMID 35295962, 2022). "We concluded that hsa-miR-30a-3p significantly suppresses MMP2 and MMP9 expression and cell invasiveness in BC, which may become a potential tool of miRNA-based cancer therapy targeting MIBC." (PMID 35449123, 2022). "Among them, MMP-2 and MMP-9 are highly-expressed in malignant tumors, and have been proved to have participated in degradation of the ECM, a crucial component of the basal membrane, leading to cancer metastasis." (PMID 35812733, 2022). "Moreover, CCL2–CCR2 signaling enhances metalloproteinase MMP2 and MMP9 production in human chondrosarcoma and hepatoma cells, which elicits detrimental effects on cancer cell invasion and motility." (PMID 35408440, 2022). "We hypothesised that MMP2 and MMP9, both of which are relevant for ECM degradation, may be necessary for peritoneal invasion and cancer cell colonisation." (PMID 35954423, 2022). "In addition to NAT, the long non-coding transcript of MMP2 (LncRNA-MMP2-2) is also induced by TGF-β1 and contained in exosomes to promote host gene MMP2 expression for enhancing cancer cell migratory ability." (PMID 35736633, 2022). "Furthermore, TGF-β-mediated signaling induces expression of MMPs, notably MMP2 and MMP9, potentially facilitating the migration and invasion of cancer cells." (PMID 36012449, 2022). "Furthermore, alcohol can directly upregulate the expression of vimentin and matrix metalloproteinases MMP-2, MMP-7, and MMP-9, which are known to promote an epithelial–mesenchymal transition, cancer cell aggressiveness, and extracellular remodelling." (PMID 35276890, 2022). "CA reveals action against numerous cancers, inhibiting the exaggerated creation of ROS and supporting cancer cell destruction via DNA oxidation and angiogenesis by acting to decrease VEGF-mediated vascularization and repression of MMP-2 and MMP-9." (PMID 35355732, 2022). "Moreover, MMP2 and MMP9, which were reported to be downstream of SKA1 or TRPV2 in many other cancers, were found to be downregulated in ESCC cells when SKA1 or TRPV2 was knocked down by siRNAs." (PMID 35813298, 2022). "In addition, PPP4C promotes the expression of matrix metallopeptidase (MMP)-2 and MMP-9 through the PI3K/AKT signaling pathway, thus promoting the invasion and metastasis of cancer cells." (PMID 34964699, 2022). "Furthermore, MFG-E8 promotes the secretion of MMP2, a potent activator of TGF-β1, in macrophages and cancer cells." (PMID 35440618, 2022). "However, data concerning a correlation between high MMP-2 and MMP-9 levels and carcinoma types according to the Lauren’s classification were contradictory." (PMID 35163805, 2022). "Therefore, in our previous studies, we also compared the serum levels of MMP-2 and TIMP-2 in patients with CRC with their expression in cancer cells, inflammatory infiltrate cells and colorectal cells from adjacent normal tissue." (PMID 34071492, 2021). "Furthermore, the mRNA levels of MMP-2 and MMP-9, extracellular matrix-degrading enzymes required for the cancer invasive process, were significantly downregulated by ETD in a dose-dependent manner." (PMID 33758209, 2021). "In addition, multiple studies in various cancer cell lines showed that UA down-regulates two gelatinases responsible for the breakdown of extracellular matrix involved in cancer metastasis, matrix metalloproteinase 9 (MMP-9), and MMP-2." (PMID 34439409, 2021).
cancer (continued). "MMP2 and MMP9 overexpression, and links to the progression of a wide range of cancers, have been well-documented and due to their involvement in the pathophysiology of disease, MMP2 and MMP9 are generally considered as the most important enzymes among the MMPs47,81,84." (PMID 33958632, 2021). "Data above showed that MMP-2 is required for CTX to increase cancer cell number at 3 h but not for CTX to increase vascular permeability." (PMID 34638621, 2021). "Here, in order to unveil the perturbed proteomic signal during MMP-2 induced cancer progression, we analyzed plasma proteome of CRC patients according to disease progression, HCT116 cancer secretome upon MMP-2 knockdown, and publicly available CRC tissue proteome data." (PMID 34429501, 2021). "To gain first insights into the underlying molecular differences of cellular invasiveness, we analyzed the activity of matrix metalloproteinase 2 (MMP2), a key enzyme responsible for extracellular matrix (ECM) degradation thereby enhancing cancer cell dissemination." (PMID 34116687, 2021). "MMP2 and MMP9 in particular among the MMPs are considered to be highly valuable enzymes due to the important role they play in disease pathogenesis such as cancer and Alzheimer’s disease." (PMID 34209215, 2021). "Notably, the production of matrix metalloproteinases MMP-2 and MMP-9, which are crucial for cancer cell invasion and metastasis, was significantly suppressed in response to rSmeg-hMIF-hIL-7 treatment." (PMID 34389619, 2021). "Indeed, preclinical studies have shown that the increased expression of TrkB promotes the suppression of E-cadherin expression and enhances the activity of the matrix metalloproteinase-2 (MMP-2) in lung SCC cells, promoting cancer aggressiveness." (PMID 33807876, 2021). "After MMP-2 digestion, ELP-mmpL-CPP-Dox killed more cancer cells than did ELP-CPP-Dox." (PMID 33498762, 2021). "Thus, the inhibition of MMP-2 and MMP-9 activities can be employed as an important anti-metastasis strategy to prevent cancer cell dissemination." (PMID 34769032, 2021). "Among the various members of the MMP family, MMP2 and MMP9 have major roles in cancer metastasis." (PMID 34211571, 2021). "In addition, knockdown of P4HA1 inhibited the expression of MMP2 and MMP9, which were widely considered to relate to cancer invasion." (PMID 34659558, 2021). "Importantly, MMPi abolished the effect of CTX-serum, supporting the idea that MMP-2, a CTX-increased factor in the serum, remodels ECM to increase its adhesiveness to cancer cells." (PMID 34638621, 2021). "Upregulation of MMP-2 and MMP-9 are particularly noted in cancer cells." (PMID 35366261, 2021). "MMP-2 and MMP-9 play major roles in cancer cell invasion and metastasis." (PMID 34770993, 2021). "MMP-2 and MMP-9 are two key enzymes in the process of cancer cell invasion and metastasis." (PMID 34659556, 2021). "Numerous studies have demonstrated that the expression of MMP2 and MMP9 in cancer cells could be directly mediated by activation of the PI3K/AKT/mTOR pathway." (PMID 34758823, 2021). "Various in vitro and in vivo assays highlight that ginsenosides including compound K (CK), Rg1, Rg3, Rh1, Rh2 and Rd reduced metastatic abilities of various tissue-specific cancer cells by down-regulating the transcriptional expressions of several MMPs (MMP-1, MMP-2, MMP-3, MMP-7, MMP-9 and MMP-13)." (PMID 33671187, 2021). "In contrast to MMP-2 and MMP-3, high MMP-7 levels were frequently detected in advanced clinical stage NPC patients in this study, suggesting a possible role for MMP-7 in the determination of advanced cancer in NPC." (PMID 34078895, 2021). "In particular, MMP-2 and MMP-9 play important roles in cancer infiltration." (PMID 33441903, 2021). "Furthermore, VPA-treated A549 cells showed decreased expression of CD44v6, MMP-2, and MMP-9 considered as metastasis indicators in cancer." (PMID 34400947, 2021).
cancer (continued). "Also, it has been shown that the ERK signaling pathway stimulates MMP2 and MMP9 activity though triggering the ADAM17, a metalloprotease enzyme highly expressed in various human disorders, including cancers." (PMID 34011277, 2021). "However, it was known more recently that radiation promotes the remnant cancer cells to escape immune system and distant metastasis through the increased expression of TGF-β, PD-L1 and MMP-2 in cancer cells." (PMID 33793576, 2021). "In vitro studies have also demonstrated the impact of P. gingivalis and F. nucleatum on the upregulation of matrix metalloproteinases, including MMP-2, MMP-3, and MMP-9, which degrade the extracellular matrix and the basement membrane enabling cancer cells to invade and translocate to other sites." (PMID 34299675, 2021). "This anti-cancer outcome directly correlates with downregulation of various signaling cascades such as expression of PI3K (phosphatidylinositol 3-kinase), FAK (focal adhesion kinase), and MMP-2 and MMP-9 (matrix metalloproteinase-2 and 9)." (PMID 35008495, 2021). "Since MMP2 and MMP9 are two of the most characterized MMPs in cancer metastasis, and since Ankrd2 modulates cell motility, we tested the possibility that Ankrd2 might promote invasion by modulating the activity of these MMPs." (PMID 33419058, 2021). "MMP-2 and MMP-9 play a key role in cancer migration and invasion." (PMID 34356663, 2021). "Moreover, lycopene-mediated regulation of expression of MMP-2 and MMP-9 in several cancer cell lines inhibits the cancer growth and proliferation." (PMID 34094892, 2021). "Thus, MMP-2, which is up-regulated in mouse serum by CTX, is functionally important for CTX to increase intravascular arrest of cancer cells." (PMID 34638621, 2021). "MMP-2 mRNA was expressed in nonneoplastic stromal cells as well as cancer cells, and double immunofluorescence staining confirmed M2 positivity." (PMID 33441903, 2021). "In addition, IL-6 secreted from cancer cells facilitates angiogenesis and stromal changes to the CAF phenotype, increasing the levels of matrix metalloproteinase-2 and -9 (MMP-2 and MMP-9), which trigger ECM proteolysis." (PMID 34957091, 2021). "Overall, these data indicated that the inhibitory impact of sFLT01 on cancer cells growth and invasiveness could be mediated through the modulation of VEGF/GRP78/MMP2&9 axis and activation of TIMPs." (PMID 34011277, 2021). "MF HSC/MPP showed a high expression of immune and inflammatory pathways (HLA genes, GBP4, and IFITM1), a matrix- and collagen-degrading enzyme (MMP2), and genes with oncogenic function (MYCN, KRT8, and KRT18) that have been correlated with cancer progression and poor survival." (PMID 34525349, 2021). "Various studies demonstrated that oridonin could inhibit the expression of MMP-2 and MMP-9 in various cancers such as breast, acute myeloid leukemia bone, and ovarian cancer." (PMID 33546106, 2021). "This was not caused by the downregulation of MMP2 gene expression, but rather the downstream effects of trichostatin A-induced RECK upregulation, which decreased CL-1 cancer cell invasion." (PMID 33920915, 2021). "Moreover, the downstream target genes of Akt, including CDK4, MMP‐2 and MMP‐9, are involved in cancer cell proliferation, migration and invasion." (PMID 34709758, 2021). "The function of MMP2 and MMP9 are very well-characterized in cancer cell metastasis." (PMID 33996789, 2021). "In cancer cell line models CD44+ cells demonstrated significantly elevated MMP-2 and MMP-9 levels compared to CD44- cells, further indicating that CD44 is involved in MMP-2 and MMP-9 expression." (PMID 33335857, 2020). "miR-130b could be identified as a promotor of MMP-2 activity and invasion of NSCLC cancer cells in vitro by downregulation of TIMP-2." (PMID 33469537, 2020).